ACY3 (aminoacylase 3)
Description:
Plays an important role in deacetylating mercapturic acids in kidney proximal tubules. Also acts on N-acetyl-aromatic amino acids (By similarity).
Synonyms: ACY-3; HCBP1; ASPA2; MGC9740
Tractability: Antibody: UniProt places it where antibodies can reach, with high confidence; its Gene Ontology location is reachable by antibodies, with medium confidence.
Gene: Protein-coding gene on chromosome 11 (67,642,551 to 67,650,900, reverse strand). Ensembl gene ENSG00000132744.
Subcellular location: Apical cell membrane; Cytoplasm
Pathways (Reactome):
Metabolism: Aflatoxin activation and detoxification
Gene Ontology:
Molecular function: protein binding; aminoacylase activity; hydrolase activity, acting on carbon-nitrogen (but not peptide) bonds, in linear amides; hydrolase activity, acting on ester bonds; identical protein binding
Cellular component: apical plasma membrane; cytoplasm; extracellular exosome; cytosol; membrane
Genetic constraint (gnomAD): Loss-of-function variants: 20 observed, 24.3 expected, observed/expected ratio (o/e) 0.82, 90% interval 0.58 to 1.2. The upper end of that interval is the gene's LOEUF score, 1.2, which puts it in group 5 of 6, group 1 being the genes least tolerant of losing a copy. Missense variants: 423 observed, 424.93 expected, observed/expected ratio (o/e) 1, 90% interval 0.92 to 1.08. Synonymous variants: 174 observed, 186.74 expected, observed/expected ratio (o/e) 0.93, 90% interval 0.82 to 1.06.
Homologues: Orthologues: chimpanzee ACY3 (99% identical), macaque ACY3 (95% identical), guinea pig ACY3 (71% identical), mouse Acy3 (69% identical), rat Acy3 (58% identical), tropical clawed frog acy3 (49% identical), zebrafish acy3.1 (45% identical), zebrafish acy3.2 (43% identical). Paralogues in human: ASPA (43% identical).
Diseases named in the same sentence as ACY3 in open-access papers:
ACY3 is named in the same sentence as 7 diseases in open-access papers, as found by Europe PMC text mining. Sharing a sentence is not in itself a finding about the gene and the disease. The quoted sentences say what the papers report.
Arrhythmia (1 paper, 2016). Any cardiac rhythm other than the normal sinus rhythm. "No relation between ACY3 and cardiac function or arrhythmias has been described previously." (PMID 27589061, 2016).
Huntington disease (1 paper, 2022). Huntington disease (HD) is a rare neurodegenerative disorder of the central nervous system characterized by unwanted choreatic movements, behavioral and psychiatric disturbances and dementia. "ACY3 has rarely been reported but also may contribute to pathogenesis of Huntington disease (HD) by altering binding of transcriptional factors." (PMID 35392800, 2022).
ACY3 also shares sentences with these, for which no sentence is quoted: bacterial infections (1 paper); hepatoma (1); lung carcinoma (1); thyroid cancer (1); tumor (1).